BCL2 (BCL2 apoptosis regulator)
Diseases named in the same sentence as BCL2 in open-access papers (continued):
Sharing a sentence is not in itself a finding about the gene and the disease.
breast carcinoma (continued). "Combinatorial treatment of genistein and hypericin in human breast cancer cells resulted in the reduction of Bcl-2 expression while an increase in Bax expression suppressed Akt and ERK1/2 phosphorylation." (PMID 34768743, 2021). "Overexpression of the antiapoptotic protein BCL-2 is correlated with estrogen receptor (ER) expression in breast cancer and plays an important role for disease pathophysiology." (PMID 34063475, 2021). "Observations from our lab and otherssuggest that different breast cancer cell lineages are dependent on distinct Bcl-2 familymembers." (PMID 34124284, 2021). "Amplified signaling of IL17RB and related ligand IL17B enhanced tumorigenicity in breast cancer cells and activated NF-κB to upregulate anti-apoptotic factor Bcl-2 and induced etoposide resistance." (PMID 34724890, 2021). "Prostate cancer, breast cancer, B-cell lymphomas, and colorectal cancer,for example, all have high levels of Bcl-2." (PMID 35574508, 2021). "Chrysophanol inhibits proliferation and induces apoptosis through NF-κB/cyclin D1 and NF-κB/Bcl-2 signaling cascade in breast cancer cell lines." (PMID 34519612, 2021). "In breast cancer, BCL-2 is an estrogen-responsive gene overexpressed in ∼85% of estrogen receptor (ER)-positive breast cancers." (PMID 34581776, 2021). "In breast cancer, METTL3 directly targets BCL-2 by increasing the extent of the m6A modification of BCL-2 to increase its RNA and protein expression levels, thereby regulating the proliferation and apoptosis of breast cancer." (PMID 34315512, 2021). "VD3 supplementation increased IRE-1α and Bcl-2 and reduced pBcl-2 protein levels in the mammary tumors." (PMID 34069442, 2021). "CHIP can act as an activator of Bcl-2 expression levels to suppress breast cancer (BC) malignant progression." (PMID 33935743, 2021). "They found that thymoquinone can increase PPARγ activity and downregulate the expression of Bcl2 and Bcl-xL in breast cancer." (PMID 33197888, 2020). "The paclitaxel-sensitizing effects of miR-7-5p are reversed by the restoration of BCL-2 in breast cancer cells." (PMID 33066509, 2020). "We indeed observed that CAF modulate BCL-2 dependence in luminal breast cancer cells via IL-6 signaling, shifting from a BCL-2 to a MCL-1 survival dependence." (PMID 32722518, 2020). "On a wide study of multiple solid tumor cell lines, MCL-1 mRNA was the anti-apoptotic BCL-2 member with the highest levels in glioma, lung, renal, prostate, ovarian and breast cancer lines." (PMID 32131385, 2020). "Quercetin decreases the viability and proliferation of MCF-7 breast cancer cells through apoptosis activation, via increasing the levels of Bcl-2-associated X protein (BAX) and caspase-3 expression and decreasing Bcl-2 expression." (PMID 32102219, 2020). "For example, miR-184 inhibits the proliferation and invasion of human glioma and breast cancer cells, and blocks the growth and survival of nasopharyngeal carcinoma cells by directly targeting BCL2 and C-MYC19." (PMID 32906580, 2020). "Achari and colleagues established that miR-34c exerts the antitumor activity in breast cancer by several mechanisms including the G2/M cell cycle arrest and the suppression of BCL2 and SIRT1." (PMID 33396625, 2020).
breast carcinoma (continued). "In sensitive breast cancer cell lines ATRA can down-regulate the expression of some anti-apoptotic molecules as Bcl-2, cdk2, cyclin D1, and survivin, that are overexpressed in one third of breast cancer types." (PMID 32012980, 2020). "On the other hand, expression of the anti-apoptotic BCL2 gene in the treated breast cancer cell line has significantly decreased compared with control cells representing a probable reduction in survival signals in these cancer cells." (PMID 32774808, 2020). "Our results also showed that LHE treatment increased cleaved PARP and decreased antiapoptotic Bcl‐2 expression in both breast cancer cell types." (PMID 33133573, 2020). "By observing the western blot and luciferase assay analysis, it was determined that miR-185-5p targeted the 3′UTR of BCL2 in the breast cancer cell." (PMID 32366289, 2020). "eIF4E silencing also increases Bax/Bcl-2 ratio and sensitizes breast cancer to cisplatin, adriamycin, paclitaxel and docetaxel." (PMID 33038921, 2020). "Control of BCL2 expression via miR-24-2 (strongly upregulated in both proximal and distal tumors), has been previously reported in human embryonic kidney and breast cancer cell lines." (PMID 32293332, 2020). "Distal regulatory regions of BCL2 have been shown to target promoters based on chromatin accessibility dynamics in breast cancer." (PMID 32419250, 2020). "Troglitazone, a PPARɣ ligand, inhibits tumor growth and induces apoptosis by downregulating Bcl-2 in breast cancer cells." (PMID 33046822, 2020). "E-cadherin activated Rac signaling pathway through the transcription target of HOXA1, which can promote breast cancer cell survival by upregulating cyclinD1, c-Myc, and BCL-2." (PMID 33763449, 2020). "Increasing the BAX/BCl2 ratio is an important factor for the induction and processing of apoptosis in breast cancer." (PMID 33369440, 2020). "Nar isolated from Thymus vulgaris upregulated pro-apoptotic markers, p18, p19, p21, Bax and Bak, and downregulated anti-apoptotic markers, Cdk4, Cdk6, Cdk7, and Bcl-2 in human colorectal and breast cancer cells leading to apoptosis." (PMID 33192517, 2020). "Inhibition of glutathione is also shown to overcome the Bcl2-mediated cisplatin resistance in MCF7 breast cancer cells." (PMID 32763516, 2020). "For example, curcumin, a bioactive ingredient of the plant Curcuma longa, exerts an inhibitory effect on triple-negative MDA-MB-231 breast cancer cells through upregulation of p21 protein expression and enhancement of the Bax-to-Bcl-2 ratio." (PMID 32164337, 2020). "For example, the expression of PR showed in female breast cancer a continuous dependency on cytokeratin 8/18, cyclin D1, B cell lymphoma 2 (Bcl-2), and cyclin-dependent kinase inhibitor p21." (PMID 32188473, 2020). "As expected, treatment with ABT-737 alone was ineffective, but treatment with combination therapy led to significant improvements in tumor response and OS in-vivo in breast cancer xenografts which overexpressed BCL-2." (PMID 32131385, 2020). "TAM-derived IL-10 display increased expression of bcl-2 and STAT3 genes, and the subsequent IL-10/STAT3/Bcl-2 signaling pathway induced TAM-mediated treatment resistance on co-culturing human breast cancer cell lines (T47D, BT549) and TAMs (THP-1)." (PMID 32726950, 2020).
breast carcinoma (continued). "To note, the combined treatment has been shown to be more effective than treatment with BBR or curcumin alone in enhancing the autophagy process via the JNK/Bcl-2/Beclin-1 pathway in breast cancer cells." (PMID 32855766, 2020). "In support of this, MGE not only promoted the formation of intracellular ROS with mitochondrial dysfunction, but also activated apoptosis through regulating the expression of Bcl-2, Bax, cytochrome c, and cleaved caspase-3 in human breast cancer cells." (PMID 32774407, 2020). "BPA and 4-cumylphenol (4-CP), another E-like compound, at levels ranging from 10−9 to 10−5 M, stimulate cell proliferation and expression of ERα, pS2, and B-cell lymphoma-2 (Bcl-2) in MCF-7 breast cancer cells." (PMID 33330580, 2020). "Silencing of ITGAV inhibited cell proliferation, invasion, and self-renewal of breast cancer cell lines by altering expression of BCL2 and PXN." (PMID 32847144, 2020). "JNK was shown to directly promote breast cancer cell survival by phosphorylating Bcl2 and BclX proteins which protect mitochondrial integrity and counteract apoptosis." (PMID 33287446, 2020). "Recently, one research group identified that diosgenin promoted apoptosis and triggered cell cycle arrest at the G2/M phase through regulation of Chk1 kinase, Cdc25c pathway, and Bcl-2 in breast cancer cells." (PMID 32626765, 2020). "An analysis of the TCGA dataset showed that BCL-2 protein levels were negatively correlated with PARK2 mRNA expression in breast cancers." (PMID 32929329, 2020). "In conclusion, among the nine compounds isolated from the EA fraction of the L. cuneata methanolic extract, aviculin, a lignan glycoside, inhibited metabolic activity in breast cancer cells and induced their apoptosis via an increase in the Bax/Bcl-2 ratio." (PMID 32276430, 2020). "Abnormal STAT3 signal can cause the dysregulation of expressions of downstream genes such as Bcl-2 and promote breast cancer progression." (PMID 32760217, 2020). "Thymoquinone elevates PPAR-γ activity and downregulates the expression of genes for survivin, Bcl-xL and Bcl-2 in MDA-MB-231 breast cancer cells." (PMID 32823812, 2020). "On the other hand, overexpression of Bcl-2 protein, which is anti-apoptotic protein, contributes to the evasion of apoptosis in prostate cancer cells, glioblastoma, and breast carcinoma cells." (PMID 32075108, 2020). "In this study, we also demonstrated that miR-185-5p targeted the BCL2 in BT-474 cells, therefore, miR-185-5p significantly increased the cell apoptosis, suggesting that miR-185-5p can act as a tumor suppressor in breast cancer cells." (PMID 32366289, 2020). "We previously showed that ER+ tumors undergo apoptosis following BCL-2 inhibition, demonstrating that the executioner caspases are functional in this breast cancer subtype." (PMID 32341449, 2020). "Hinokiflavone exhibited a time‐ and dose‐dependent manner apoptosis induction by upregulating expression of Bax and downregulating Bcl‐2 in breast cancer cells." (PMID 32107809, 2020). "Our findings further showed that therapeutic inhibition of LncRNA NONHSAT141924 restrained PTX-resistance through p-CREB/Bcl-2 apoptosis signaling pathway, the major pathway involved in chemotherapy resistance for breast cancer." (PMID 32284761, 2020). "Ursolic acid promoted apoptotic cell death in human breast cancer MCF-7 cells by Bcl-2 downregulation and suppressing the expression of transcription factor FoxM1, while in MDA-MB-231 cells via mitochondrial death and extrinsic death receptor pathway." (PMID 33138135, 2020). "They investigated the influence of CLA on key apoptotic genes in human breast cancer cells and noticed that BCL-2 transcripts were significantly elevated in MDA-MB-231 cells after CLA stimulation." (PMID 31993929, 2020).
breast carcinoma (continued). "A combination of vitamin A with a chemotherapy drug or pro-apoptotic molecules potentiates breast cancer cell death by decreasing pro-survival Bcl-2, increasing pro-death Bax, and activating caspases." (PMID 32708855, 2020). "Curcumin exerted autophagy and induced apoptosis in MCF-7 breast cancer cells by downregulating the Bcl-2 signaling cascade and blocking the PI3K/Akt signaling pathway." (PMID 32823812, 2020). "Withaferin A induces apoptosis by generating reactive oxygen species and down-regulating B-cell lymphoma 2 (Bcl-2) protein in human melanoma cells and breast cancer cells." (PMID 33585254, 2020). "It has also been reported to display antiproliferation activity by inducing apoptosis and deregulation of B-cell lymphoma 2 (Bcl-2) expressions in MCF-7 breast cancer cells." (PMID 32703212, 2020). "This experiment clearly shows a significant dose-dependent increase in the Bax/Bcl-2 ratio in rat mammary tumors induced by sumac treatment, which correlates with an increase in cleaved caspase-3 expression in the treated group and higher sumac dose." (PMID 33375383, 2020). "Consistently, BC spread is faster when correlated to Bcl-2 overexpression, as well as genetic Bax ablation promotes mammary tumor development." (PMID 32517101, 2020). "The reduced expression of Bcl-2 accompanied by the increased expression of Bax was observed in the presence of simvastatin in lymphoma cells as well as in the colon and breast cancer cells." (PMID 30813251, 2019). "There was significant co-expression of TFF3 and BCl2 in breast carcinoma cases treated with neoadjuvant therapy (p = 0.0152) suggesting anti-apoptotic role of TFF3." (PMID 30744593, 2019). "TPGS is known to activate both caspase-dependent and caspase-independent PCD in breast cancer cell lines, inducing the downregulation of Bcl-2, the translocation of AIF and Endo G to the cytosol and the cleavage of caspase-7 and PARP19." (PMID 31591437, 2019). "Functional analysis in breast cancer cell lines demonstrated that Dab1 promoted cell apoptosis, which, at least partially, depended on its regulation of NF‐κB/Bcl‐2/caspase‐9 pathway." (PMID 30484953, 2019). "In breast cancer, koumine affected the apoptotic Caspase 3/Bcl-2 cascades to induce G2/M arrest and apoptosis in breast cancer MCF-7 cells." (PMID 31581704, 2019). "Its protein expression was significantly associated with ER expression in breast cancer tissues, and it had distinct regulatory effects on HER2 and Bcl-2 expression in ER+ PR+ HER2− and ER− PR− HER2− cell lines." (PMID 30866857, 2019). "In conclusion, our in vitro studies, using a panel of GBM, melanoma, and breast cancer cell lines showed that Bcl-2 inhibitor ABT-737 reversed the resistance of tumor cells to IT treatment." (PMID 30625226, 2019). "The expression levels of β2M, HIF-1α, p-CREB, VEGF, p-SGK1, p-ERK1/2, and Bcl-2 were significantly higher in cancer tissues of patients with luminal A breast cancer compared to adjacent tissues (p < 0.05)." (PMID 30866857, 2019). "The question of the stromal influence on BCL-2 dependency is particularly apposite in breast cancer given the established impact of a hijacked stroma on this disease progression and therapeutic response." (PMID 30631150, 2019). "The expressions of Bcl-2 in these three cell lines decreased, while that of cleaved caspase-3 in three breast cancer cell lines significantly increased after Pec.-treated." (PMID 31649548, 2019). "In this study, we showed that lncUSMycN knockdown probably induced apoptosis through the suppression of Bcl-2 and overexpression of Bax in breast cancer cells." (PMID 31102367, 2019). "A previous study documented that overexpression of BTG1 induces apoptosis of breast carcinoma cells, accompanied by a decline in the Bcl-2 level and an increase in the Bax and Caspase 3 levels." (PMID 31324015, 2019).
breast carcinoma (continued). "A significant correlation between the ratios of BAX/ BCL2 was reported to segregate radiosensitive versus radio-resistant breast cancer patients." (PMID 31014274, 2019). "According to previous studies, both STC2 and BCL2 are estrogen-responsive genes that are upregulated in luminal breast cancers and correlate with a better prognosis 18-22." (PMID 31410192, 2019). "Many studies in human breast cancer have reported the protective effect of Bcl-2 positivity in the luminal phenotype." (PMID 30630524, 2019). "Here, we shed light on the pro-survival Bcl-2 proteins in breast cancer using different bioinformatic approaches, linking -omics with structural data." (PMID 31825969, 2019). "The intrinsic apoptosis pathway was induced by AgNPs and PDT combination therapy through up-regulation of pro-apoptotic proteins of the Bax and downregulation of the anti-apoptotic proteins Bcl-2 in MCF7 breast cancer cells." (PMID 31220110, 2019). "The ABv+anti-PD-1 combination showed remarkable efficacy in a number of breast cancer models, which was somewhat surprising in light of the fact that BCL-2 dependency is most often observed in hematologic malignancies." (PMID 30728358, 2019). "Altogether, these results show that factors secreted by CAFs led to MCL-1 induction and MCL-1 dependent resistance to the apoptotic effects of BCL-2 inhibition in the neighboring breast cancer cells." (PMID 30631150, 2019). "More than half of the breast cancers with MYC-high status expressed a high level of BCL-2, BCL-XL, or MCL-1." (PMID 30728358, 2019). "In previous studies, we have unveiled a pro-apoptotic role of miR-195 in breast cancer and we have demonstrated that miR-195 downregulates Bcl2 by direct binding to its 3ʹUTR Sequence." (PMID 30932749, 2019). "In contrast, MCM4 gene promoter was hypermethylated in breast cancer and BCL2, PIK3R1 gene promoter were hypomethylated." (PMID 31777591, 2019). "Studies based on ex vivo cultures of human luminal breast cancer tissues further argue that the contribution of stroma-derived signals to MCL-1 expression shapes BCL-2 dependency." (PMID 30631150, 2019). "In breast cancer, venetoclax is combined with faslodex to treat endocrine therapy resistant hormone receptor positive breast cancer, given that functional estrogen receptor (ER) transcriptionally up-regulates BCL-2." (PMID 31370269, 2019). "This is the first study that investigates the prognostic significance of Bcl-2 in feline mammary carcinomas." (PMID 30630524, 2019). "In human breast cancer cells, koumine promotes apoptosis and cell cycle arrest in G2/M phase via reducing Bcl2 and increasing the pro-apoptotic factors Bax and Caspase-3." (PMID 31581704, 2019). "Ezrin, LaminA/C, cleaved caspase‐3, Bcl‐2, and Bax protein expressions in tumor tissues and para‐carcinoma tissues of breast cancer patients were detected via Western blotting." (PMID 31578772, 2019). "The mechanisms of acute Mcl-1 upregulation in response to Bcl-2/Bcl-xL inhibition remain undefined in in ERα+ breast cancers." (PMID 31595181, 2019). "We report here that blockade of Bcl-2 or Bcl-xL, alone or together, rapidly induced mTOR signaling in ERα+ breast cancer cells, rapidly increasing cap-dependent Mcl-1 translation." (PMID 31595181, 2019). "PEITC can also induce apoptosis from the mitochondria in breast cancer cells by caspase activation, as well as changes in the Bac/Bcl-2 ratio following the release of cytochrome c, all significant elements of the intrinsic apoptotic pathway." (PMID 30066177, 2019).